CSPG4 (chondroitin sulfate proteoglycan 4)
Diseases named in the same sentence as CSPG4 in open-access papers (continued):
Sharing a sentence is not in itself a finding about the gene and the disease.
leukemia (continued). "To date, no comprehensive studies analyzing CSPG4 expression on leukemia cells using the 9.2.27 antibody exist, providing an avenue for future research." (PMID 31779130, 2019). "In aggregate, we wish to highlight the therapeutic potential of CSPG4-CAR T cells as a possible back-up modality for B-ALL relapsing to CD19-CAR T cell therapy, with special emphasis on MLL leukemias, which harbor the potential to undergo a lineage switch and shed all B cell-associated antigens." (PMID 31195686, 2019). "In aggregate, a possible merit connoted with CSPG4-CAR-T cells in AML is the exertion of anti-leukemia activity against CSPG4-positive blasts without affecting HSCs, which were found to be universally CSPG4-negative." (PMID 31779130, 2019). "To test the cytolytic activity of CSPG4-CAR T cells, CEA control T cell, and mock T cells toward KOPN8 leukemia cells, we first performed a 4 h degranulation assay analyzing CD107a upregulation on CD8+ T cells after co-incubation with T2.A1, KOPN8, and A375M cells." (PMID 31195686, 2019). "Moreover, CSPG4 has been found on the surface of MLL-rearranged leukemia cells, a form that accounts for around 10% of all leukemias." (PMID 31195686, 2019). "In the current study, we could show that those CSPG4-CAR T cells antigen-specifically react also toward MLL leukemia cells, providing the only report on CSPG4-CAR T cells against leukemia to date." (PMID 31195686, 2019). "In aggregate, these results proved that CSPG4-CAR T cells evince an antigen-specific secretion pattern of Th1 cytokines in response to KOPN8 leukemia cells, without IL-2 and IL-4 production." (PMID 31195686, 2019). "Hence, the absent IL-2 production by CSPG4-CAR T cells in response to leukemia cells might be beneficial to prevent a surge of regulatory T cells." (PMID 31195686, 2019). "We obtained CSF from four patients with DIPG/DMG and four patients with leukemia (negative control group) and performed western blot analysis with antibodies against the N-termini of NLGN3 and CSPG4." (PMID 40791371, 2025). "Consistently, all studies involving CSPG4-CAR T cells have been focused on solid tumors, and no data concerning leukemia have been published." (PMID 31195686, 2019). "Additionally, CSPG4-CAR T cells did not secrete IFNγ upon co-incubation with T2.A1 cells, confirming antigen-specific IFNγ secretion towards CSPG4-positive KOPN8 leukemia cells." (PMID 31195686, 2019). "Moreover, CSPG4-CAR T cells exhibited a significantly higher CD69 and CD25 expression upon co-culture with KOPN8 leukemia cells as compared to co-incubation with CSPG4-negative T2.A1 cells, further corroborating antigen-specific activity of CSPG4-CAR T cells in response to KOPN8 leukemia cells." (PMID 31195686, 2019).
osteosarcoma (14 papers, 2014 to 2025). A usually aggressive malignant bone-forming mesenchymal neoplasm, predominantly affecting adolescents and young adults. "In summary, the HuDo-CSPG4 vaccine has been shown to be safe and effective in inducing anti-CSPG4 immunity in dogs affected by osteosarcoma, leading to prolonged survival compared to control groups." (PMID 40284831, 2025). "Although B7H3, L1CAM, CSPG4, and Lewis Y were also overexpressed by some osteosarcoma cell lines, the ADTC potency of their respective BsAb was much weaker than GD2-BsAb or HER2-BsAb." (PMID 33303017, 2020). "These preliminary data suggest a widespread expression of CSPG4 in appendicular osteosarcomas (unpublished data), the most common primary canine malignant bone tumor." (PMID 28668095, 2017). "In a pilot veterinary study, 25 dogs with limb amputated, CSPG4-positive, stage I–III appendicular osteosarcoma were involved." (PMID 40284831, 2025). "Currently, potential effective targets for CAR-T cell therapy in osteosarcoma include HER2, IGF1R, ROR1, EphA2, CSPG4, folate receptor with EC17, B7-H3, GD2, NKG2D, ALCAM/CD166, IL-11Rα, and FAP." (PMID 38187386, 2023). "Indeed, our immunohistochemical analysis of CSPG4 expression performed on a cohort of 29 canine osteosarcoma patients, revealed 23 (79%) positive and 6 (21%) negative cases." (PMID 28668095, 2017).
mesothelioma (13 papers, 2014 to 2025). A usually malignant and aggressive neoplasm of the mesothelium which is often associated with exposure to asbestos. "On the basis of our findings in mesothelioma, we concluded that the association of certain cellular markers such as lipid rafts with TNTs is an indicator of cell invasion (i.e., CSPG4) and that this leads to increased formation of TNTs." (PMID 30333973, 2018).
soft tissue sarcoma (11 papers, 2017 to 2023). A malignant neoplasm arising from muscle tissue, adipose tissue, blood vessels, fibrous tissue, or other supportive tissues excluding the bones. "During the last years, CSPG4 was described as another potential target of cellular immunotherapy in cancers, and more recently soft tissue sarcomas, including GIST." (PMID 35267618, 2022). "Recently, CSPG4-specific chimeric antigen receptor (CAR)-redirected cytokine-induced killer lymphocytes (CSPG4-CAR.CIKs) effectively targeted multiple soft tissue sarcomas (STS) histotypes in vitro and in vivo." (PMID 35267618, 2022). "Our data suggest that targeting Ng2/Cspg4 can be developed into a novel therapeutic approach for soft-tissue sarcomas expressing this transmembrane proteoglycan." (PMID 29196603, 2018). "Data here suggest that NG2/CSPG4 mAb–based immunotherapy could be developed into an approach for the treatment of NG2/CSPG4-expressing soft-tissue sarcomas." (PMID 29196603, 2018). "Taken together, these data raise the possibility that deleting Ng2/Cspg4 at tumor initiation activates IGF signaling, a pathway known to positively regulate soft-tissue sarcoma growth, whereas in established tumors, there is an opposite effect." (PMID 29196603, 2018). "In soft-tissue sarcomas, NG2/CSPG4 expression is correlated with tumor progression." (PMID 29196603, 2018).
head and neck squamous cell carcinoma (9 papers, 2017 to 2026). A squamous cell carcinoma that arises from any of the following anatomic sites: lip and oral cavity, nasal cavity, paranasal sinuses, pharynx, larynx, and salivary glands. "To date, only one CSPG4-targeted CAR T cell construct has progressed to phase 1/2 clinical trial (ClinicalTrials.gov, NCT06096038) for patients with head and neck squamous cell carcinoma (HNSCC)." (PMID 39409881, 2024).
ovarian carcinoma (8 papers, 2022 to 2025). A malignant neoplasm originating from the surface ovarian epithelium. "Decitabine, a DNMTi, has been shown to induce the expression of chondroitin sulfate proteoglycan 4 (CSPG4) on ovarian cancer cells, such as SKOV-3, in a dose-dependent manner." (PMID 41029427, 2025). "By demethylating the CSPG4 promoter, decitabine converts over 50% of treated ovarian cancer cells into CSPG4-positive targets, enabling effective targeting by CSPG4-specific CAR T-cells." (PMID 41029427, 2025). "The CSPG4 expression was relatively weak in normal stroma and the epithelial surface of the ovaries compared to the ovarian cancer region." (PMID 38338902, 2024). "The results indicated that CSPG4-redirected CAR-Ts mediated effective target antigen-specific antitumor activity against ovarian cancer cells induced to express CSPG4, in four different effector-to-target ratios." (PMID 38146364, 2023). "Regarding further steps towards a potential clinical translation of targeting decitabine-upregulated CSPG4 on ovarian cancer cells using CSPG4-specific CAR-T cells, our data gathered from the SKOV-3 model provide several cues for further in vivo testing." (PMID 36291817, 2022). "In aggregate, we generated proof-of-concept data paving the way for the further exploration of CSPG4 as an inducible antigen for CAR-T cells in ovarian cancer." (PMID 36291817, 2022). "First, we demonstrated dose-dependent decitabine-mediated upregulation of CSPG4 on SKOV-3 ovarian cancer cells." (PMID 36291817, 2022). "On account of our data, we encourage a comprehensive screening of primary ovarian cancer cells for decitabine-mediated inducibility of CSPG4." (PMID 36291817, 2022). "Here, we introduced the potential of CSPG4 as an inducible target antigen for CAR-T-cell therapy of ovarian cancer cells." (PMID 36291817, 2022). "The goal of the current study was to employ CSPG4-CAR-T cells generated by mRNA-electroporation to target CSPG4-negative SKOV-3 ovarian carcinoma cells upon decitabine-mediated up-regulation of CSPG4." (PMID 36291817, 2022). "This corroborates the basic concept of decitabine-mediated CSPG4 upregulation in neoplastic cells, with special emphasis on ovarian cancer cells with minimal CSPG4 expression." (PMID 36291817, 2022). "Although we observed solid decitabine-mediated CSPG4-upregulation in over 50% of ovarian cancer cells, long-lasting remissions are predicated on elimination of the whole tumor including all antigen-negative cells." (PMID 36291817, 2022). "In the present work, we explored the potential of CSPG4 as an inducible secondary target antigen for CAR-T-cell therapy of solid tumors using SKOV-3 ovarian cancer cells as targets." (PMID 36291817, 2022). "Collectively, we want to shine light on the therapeutic potential of CSPG4 as an inducible secondary antigen for CAR-T-cell therapy of ovarian cancer." (PMID 36291817, 2022). "Using CSPG4-specific T cells, we demonstrate CSPG4-directed killing of decitabine-treated ovarian carcinoma cells, thereby adding CSPG4 to the repertoire of target antigens for ovarian cancer." (PMID 36291817, 2022). "By optimizing decitabine dosing, we converted more than 50% of treated ovarian carcinoma cells to CSPG4-positive cells." (PMID 36291817, 2022). "In sum, decitabine-mediated upregulation of CSPG4 on SKOV-3 ovarian cancer cells enables antigen-specific targeting using CSPG4-CAR-T cells resulting in effective CSPG4-directed target cell killing even in the presence of decitabine." (PMID 36291817, 2022). "For example, dual-targeting approaches that pair CSPG4-specific CAR T-cells with those targeting other ovarian cancer antigens, such as ErbB2, mesothelin, or TAG-72, could address this limitation." (PMID 41029427, 2025). "In ovarian cancer, CSPG4 mainly promotes invasion and metastasis." (PMID 36291817, 2022). "Here we use decitabine to induce expression of CSPG4 on SKOV-3 ovarian carcinoma cells." (PMID 36291817, 2022).
ovarian carcinoma (continued). "We show decitabine-mediated upregulation of CSPG4 on ovarian cancer cells." (PMID 36291817, 2022). "Taken together, a single application of decitabine could induce expression of CSPG4 in SKOV-3 ovarian cancer cells implying a display of a potential target by CSPG4-directed approaches." (PMID 36291817, 2022). "This is the first study to show targeting of CSPG4 on tumor cells after decitabine-mediated upregulation raising the hypothesis for CSPG4 as an inducible secondary antigen on solid tumors with special emphasis on ovarian cancer." (PMID 36291817, 2022). "Moreover, we confirmed that CSPG4-CAR-T cells retain their cytolytic capacity towards decitabine-treated SKOV-3 ovarian cancer cells in the presence of 1 μM decitabine enabling a simultaneous application of CAR-T cells together with decitabine in the clinical setting." (PMID 36291817, 2022). "A potential limitation of the concept described here, to use decitabine-mediated upregulation on ovarian cancer cells to enable targeting by CSPG4-CAR-T cells, is posed by the tumor promoting properties of CSPG4, which might additionally foster the growth of decitabine-treated tumor cells." (PMID 36291817, 2022). "Moreover, CSPG4 expression may confer selected resistance to chemotherapy on ovarian cancer cells." (PMID 36291817, 2022). "Additionally, we validate decitabine-upregulated CSPG4 as bona fide target antigen for CAR-T cells by demonstrating antigen-specific cytotoxicity as well as antigen-specific cytokine secretion of CSPG4-specific CAR-T cells in response to decitabine-treated SKOV-3 ovarian carcinoma cells." (PMID 36291817, 2022). "Finally, bulk T cells were equipped with a CSPG4-specific CAR, and antigen-specific targetability of decitabine-treated SKOV-3 ovarian cancer cells by CSPG4-specific CAR-T cells was demonstrated." (PMID 36291817, 2022). "Here, we use the FDA-approved drug decitabine to upregulate the surface antigen CSPG4 on CSPG4-negative ovarian carcinoma cells." (PMID 36291817, 2022). "Seeking to validate this dosing regimen for CSPG4 upregulation in other cell lines, we used Caov-3 ovarian cancer cells previously reported to be CSPG4-negative, and 293T cells." (PMID 36291817, 2022). "Importantly, the antigen-specific killing of decitabine-treated ovarian cancer cells is not impaired by the presence of the drug, and optimal dosing regimens (1 μM Daily for 5–8 days) have been established to maximize CSPG4 expression." (PMID 41029427, 2025). "SKOV-3 ovarian cancer cells are broadly considered CSPG4-negative." (PMID 36291817, 2022). "Hence, the use of decitabine to render tumor cells susceptible to killing by CSPG4-CAR-T cells is not exclusively restricted to SKOV-3 cells, but works also in other ovarian cancer cells, such as Caov-3, and neoplastic cells such as 293T." (PMID 36291817, 2022). "After refining a protocol enabling the decitabine-mediated conversion of more than half of initially CSPG4-negative ovarian cancer cells to CSPG4-positive cells, CSPG4-directed cytokine secretion and cytotoxicity by CSPG4-specific CAR-T cells could be demonstrated." (PMID 36768665, 2023). "Additionally, mural cell markers, such as chondroitin sulfate proteoglycan 4 (Cspg4, also known as NG2), alanyl membrane aminopeptidase (Anpep, also known as CD13), and platelet-derived growth factor receptor beta (Pdgfrb), were upregulated in FOXC2-expressing ovarian cancer cells." (PMID 36230774, 2022).
metastatic melanoma (7 papers, 2013 to 2025). A melanoma that has spread from its primary site to another anatomic site. "For instance, the anti-idiotypic mAb MK2-23, which mimic the epitope recognized by anti-CSPG4 mAb 763.74, induced specific antibody responses in metastatic melanoma patients that correlated with prolonged survival and reduced metastatic spread." (PMID 41375047, 2025). "This is a very promising finding for clinical application as targeting of CSPG4+ primary and metastatic melanoma cells can be facilitated via trans stimulation through abundantly available bystanding or even tumor-infiltrating CD20-expressing B cells." (PMID 37901209, 2023). "CSPG4-CAR.CIK were generated from peripheral blood mononuclear cells (PBMCs) obtained from metastatic melanoma patients (n = 4), and ex vivo expanded according to a previously established protocol." (PMID 37993874, 2023). "We successfully generated CSPG4-CAR.CIK from patients with metastatic melanoma and reported their intense activity in vitro against a panel of CSPG4-expressing patient-derived Mel." (PMID 37993874, 2023). "Chondroitin Sulfate Proteoglycan 4 (CSPG4) is a plasma membrane protein showing high specificity for metastatic melanoma while tyrosinase, the enzyme involved in melanin synthesis, is a biomarker useful for diagnosis of primary melanoma." (PMID 34207514, 2021). "CSPG4-targeting adoptive T cell therapy, however, might represent a powerful treatment option, especially as CSPG4 is not only expressed in primary but also metastatic melanoma cells." (PMID 37901209, 2023). "Overall, the results outlined in this study provide strong translational rationale for the design of clinical trials investigating CSPG4-CAR.CIK within the challenging setting of patients with metastatic melanoma who do not respond or relapse to treatment with immune checkpoint inhibitors." (PMID 37993874, 2023). "Further, we evaluated CSPG4 and FGF13 expression in MET and observed a non-significant or only partially significant difference in expression of CSPG4 or FGF13 among primary and metastatic melanoma, respectively." (PMID 28852061, 2017).
chordoma (6 papers, 2013 to 2025). Chordomas are rare malignant tumors arising from embryonic remnants of the notochord in axial skeleton. "Incorporating biomarkers such as CSPG4 into the diagnostic and therapeutic landscape allows for a more refined and personalized approach to chordoma treatment, where interventions are tailored based on the specific genetic makeup of individual tumors." (PMID 38731241, 2024). "Chondroitin sulfate proteoglycan 4 (CSPG4), also known as HMW-MAA, is overexpressed in chordoma and associated with disease metastasis and risk of death." (PMID 36612259, 2022). "HMW-MAA, also known as CSPG4, is detected in a majority of chordomas and chondrosarcomas and was implicated as an immunotherapy target in both tumors due to its function in cellular migration, survival, and invasion." (PMID 34067530, 2021). "A study by Schoenfeld and colleagues found that CSPG4 expression doubled the risk of death and increased the risk of metastatic disease in chordoma." (PMID 34067530, 2021). "Earlier we have described the CSPG4 expression in chondrosarcoma and chordoma comparing the genetic profile of chondrosarcoma with other cancers." (PMID 36110930, 2022). "Targeting CSPG4 may be a potential treatment modality for chordoma." (PMID 36612259, 2022). "Another genetic marker of chordomas is chondroitin sulfate proteoglycan 4 (CSPG4), which has also been targeted for immunotherapy; however, this antigen is expressed only by a fraction (~62%) of these tumors and could therefore produce false negative diagnoses." (PMID 23662285, 2013). "showcases the successful targeting of CSPG4 in diverse cancer histologies, exemplifying the potential of CAR-T cell therapy in addressing the inherent heterogeneity of chordomas." (PMID 38731241, 2024). "Taken together, these studies provide preclinical evidence for phase I clinical trials of anti-CSPG4 and B7-H3 CAR-modified T-cells in chordoma." (PMID 36612259, 2022).